CLDN3 (claudin 3)
Diseases named in the same sentence as CLDN3 in open-access papers (continued):
Sharing a sentence is not in itself a finding about the gene and the disease.
prostate tumors (3 papers, 2006 to 2023). "Our present study demonstrates that targeting Cldn3 and Cldn4 may be therapeutically useful for managing prostate tumors that have high Cldn3 or Cldn4 expression levels." (PMID 35006480, 2021). "Our in silico and RT-PCR results are consistent with numerous previous reports showing that CLDN3 and CLDN4 are overexpressed in breast, ovarian, and prostate tumors." (PMID 16836752, 2006).
Sepsis (3 papers, 2018 to 2023). Sepsis is defined as life-threatening organ dysfunction caused by a dysregulated host response to infection. "In sepsis cases, we observed an exceptionally high mean level of claudin-3, spanning a wide range." (PMID 37745643, 2023). "Metformin increased the expression of claudin 3 and 5 following areduction induced by sepsis." (PMID 32779431, 2020). "Interestingly, rats challenged with cecal ligation and puncture (as a model of sepsis) showed increased BBB permeability to Evans Blue brain staining and reduced endothelial claudin-3 and claudin-5 levels, effects that were ameliorated by the cholesterol-lowering drug simvastatin." (PMID 30687711, 2018).
amelogenesis imperfecta (2 papers, 2020). Amelogenesis imperfecta (AI) represents a group of developmental conditions affecting the structure and clinical appearance of the enamel of all or nearly all the teeth in a more or less equal manner, and which may be associated with morphologic or biochemical changes elsewhere in the body. "Mutations in CLDN10, CLDN16, and CLDN19 are associated with amelogenesis imperfecta in humans and in mice, deletion of Cldn3 significantly reduces the enamel volume compared to that of wild-type mice." (PMID 33195274, 2020). "Cldn3 knockout mice exhibit enamel defects caused by excess accumulation of extracellular matrix proteins in the forming enamel and mutations in CLDN19 are associated with Amelogenesis Imperfecta, a genetic disorder characterized by tooth enamel defects." (PMID 32760237, 2020).
atopic dermatitis (2 papers, 2024). "In atopic dermatitis patients, reduced sweat secretion was found to be due to a downregulation of the major barrier-forming TJ proteins in the sweat duct (CLDN1 and CLDN3) and in the secretory coil (CLDN3)." (PMID 38731882, 2024).
breast invasive carcinoma (2 papers, 2021). "Some claudins, including CLDN3, are considered to play an important role in the EMT and to affect the chemosensitivity of invasive breast cancer cells." (PMID 33863935, 2021).
cognitive disorder (2 papers, 2024 to 2026). A disease affects cognitive processes. "Endothelial specific inactivation of β-catenin in vivo BBB has been reported to cause significant downregulation of CLDN3, upregulation of plasmalemma vesicle-associated protein, and BBB breakdown, which leads to cognitive disorders, including Alzheimer’s disease (AD)." (PMID 38584257, 2024).
diabetes (2 papers, 2021). "Hyperglycemia is a main pathogenic factor of diabetes, and HG incubation increased claudin-1 and claudin-3 expression and reduced paracellular permeability in SMG-C6 cells." (PMID 34831451, 2021).
E. coli infection (2 papers, 2014 to 2025). "At the protein level, WB analysis consistently showed a significant downregulation in the expression of ZO-1, Occludin, and CLDN-3 following E. coli infection (p < 0.05)." (PMID 41302013, 2025). "Immunofluorescence microscopy revealed a redistribution of the tight junction proteins occludin and claudin-3 and increased expression of claudin-2 upon E. coli infection." (PMID 24637645, 2014).
endometritis (2 papers, 2022). An acute or chronic, usually bacterial infectious process affecting the endometrium. "Therefore, we furthered evaluated the effect of C. butyricum on TJP expression in the E. coli-induced endometritis model, and determined the levels of ZO-1, claudin-3, and occludin using Western blotting." (PMID 36321897, 2022).
liver cancer (2 papers, 2014 to 2020). An epithelial or non-epithelial malignant neoplasm that arises from the liver. "Here, for the first time, we showed that CLDN3 was frequently downregulated in human liver cancer and its downregulation was significantly associated with poor survival of HCC patients." (PMID 25277196, 2014). "However, we observed a significant inhibitory role of CLDN3 in liver cancer cell migration and invasion." (PMID 25277196, 2014). "A better understanding of the molecular mechanism of CLDN3 in inhibiting liver cancer cell metastasis may lead to a more effective management of HCC patients with the inactivation of CLDN3." (PMID 25277196, 2014).
metastatic cancer (2 papers, 2011 to 2014). A carcinoma which has spread from the original site of growth to another anatomic site. "Despite this, the differences in primary and metastatic cancers were not enough to indicate that a claudin-3 immunostain could provide prognostic information about the risk of metastasis." (PMID 21255442, 2011).
neutropenia (2 papers, 2022). A decrease in the number of neutrophils found in the blood. "HBD-2 ≥ 1649.02 ng/g, Claudin-3 ≥ 2488.71 pg/g, and neutropenia (defined as ≤ 1.5 × 109/L) were included in the multivariate stepwise logistic regression analysis." (PMID 36582510, 2022).
non-small cell lung carcinoma (2 papers, 2019 to 2021). A group of at least three distinct histological types of lung cancer, including non-small cell squamous cell carcinoma, adenocarcinoma, and large cell carcinoma. "In addition, one of the major contributing factors for the oncogenic role of claudin-3 in non-small-cell lung cancer (NSCLC) is its regulation of cancer stemness." (PMID 34354941, 2021). "In addition, claudin-3 is known to play an oncogenic role in non-small cell lung cancer (NSCLC)." (PMID 31861759, 2019).
ovarian adenocarcinoma (2 papers, 2009 to 2017). An adenocarcinoma that arises from the ovary. "Consist with ovarian adenocarcinoma, this study also show that the overexpression of CLDN3 is significantly correlated with recurrence, metastasis and survival." (PMID 28160565, 2017).
Salmonella Infections (2 papers, 2013 to 2022). Infections with bacteria of the genus SALMONELLA. "Our studies showed only a mild decrease in the expression of claudin 3 in naïve MafK Tg mice, which might have contributed to the increased susceptibility to Salmonella infection." (PMID 35260530, 2022). "We further found that the claudin-2 mRNA level in the colon was upregulated by Salmonella infection in vivo, whereas the other TJ proteins, claudin-3 and 7, were not changed by Salmonella infection." (PMID 23505542, 2013).
serous adenocarcinoma (2 papers, 2013). An adenocarcinoma that is characterized by the presence of papillary patterns and cellular budding. "By immunohistochemistry (IHC) claudin-3 was expressed in 81% and claudin-4 expressed in 85.7% of 84 serous adenocarcinomas respectively." (PMID 23685873, 2013). "In addition, although more than 70% of high grade serous carcinomas express abundant amounts of CLDN3 and CLDN4, the site of origin of such tumors also remains in some doubt." (PMID 23805314, 2013). "The survival analysis in this study revealed that serous adenocarcinoma patients with high claudin-3 expression had a substantially shorter survival and multivariate analysis showed claudin-3 overexpression to be an independent negative prognostic factor." (PMID 23685873, 2013). "Since the normal ovarian surface epithelium does not express either of these proteins, if serous carcinomas arise from this epithelium then a fraction must undergo a mesenchymal-to-epithelial transition (MET) during which the expression of CLDN3 and CLDN4 is up-regulated." (PMID 23805314, 2013).
thyroid cancer (2 papers, 2013 to 2021). "The overexpression of CLDN3 was also considered to be correlated with thyroid cancer and other malignancies." (PMID 34805166, 2021).
urothelial carcinoma (2 papers, 2011 to 2024). A malignant neoplasm derived from the transitional epithelium of the urinary tract (urinary bladder, ureter, urethra, or renal pelvis). "In urothelial carcinoma high CLDN3 was linked to high grade (p < 0.0001) and nodal metastasis (p = 0.0111)." (PMID 39658782, 2024). "That not only downregulation but also upregulation can be associated with tumor progression in a tumor type dependent manner is demonstrated in our study by the strong relationship between CLDN3 upregulation and grade and stage progression in urothelial carcinomas." (PMID 39658782, 2024).
abortion (1 paper, 2022). the ending of pregnancy by removing a fetus or embryo before it can survive outside the uterus. "We evaluated the expression of claudin-2, claudin-3, and claudin-10 in the uterine samples from IL-22−/− and WT mice after LPS-triggered abortion." (PMID 36091010, 2022).
alcoholic cirrhosis (1 paper, 2024). "The blood claudin 3 level was not significantly different between patients with viral and mixed viral and alcoholic cirrhosis (n = 0.678)." (PMID 38543514, 2024).
allergic rhinitis (1 paper, 2023). Inflammation of the nasal mucous membranes caused by an IgE-mediated response to external allergens. "This study assessed the mRNA expression levels of various tight junctions, including occludin (OCLN), claudin-3 and −7 (CLDN3 and CLDN7), desmoglein 3 (DSG3), and thymic stromal lymphopoietin (TSLP) in 30 individuals with Allergic Rhinitis (AR) and 30 non-allergic controls." (PMID 37692890, 2023).
aneurysm (1 paper, 2025). Bulging or ballooning in an area of an artery secondary to arterial wall weakening. "Serum CLDN3 and CLDN5 levels were measured on days 1, 5, and 9 post-ictus and compared with healthy and aneurysm-bearing controls." (PMID 41114786, 2025).
asthma (1 paper, 2025). "Analysis of tight‐junction gene sets revealed the reduced expression of a whole cluster of genes such as OCLN, CLDN3, CLDN4, NRAS, HCLS1, MYH10 in virus‐infected cells from patients with asthma in comparison to the controls." (PMID 39466641, 2025).
autoimmune disease (1 paper, 2022). A disorder resulting from loss of function or tissue destruction of an organ or multiple organs, arising from humoral or cellular immune responses of the individual to their own tissue constituents. "Confirming these data, mice lacking claudin-3 showed impaired BCSFB function and a faster onset and increased EAE severity, clearly indicating a role for claudin-3 in ChP breakdown in CNS autoimmune diseases." (PMID 36034148, 2022).
Barrett’s oesophagus (1 paper, 2023). "Moreover, the expression of CLDN3 and CLDN4 was significantly elevated both in Barrett’s oesophagus and OAC in comparison to the foveolar epithelium, while in OAC, the expression of CLDN2 was significantly higher in comparison to that in Barrett’s oesophagus." (PMID 38201579, 2023).
Chronic colitis (1 paper, 2023). A chronic inflammatory disease of the large intestine (colon, cecum and rectum). "Considering that IBD is a chronic inflammatory condition, we further examined whether Cldn3 deficient mice were also susceptible to chronic colitis." (PMID 38010872, 2023).
colorectal neuroendocrine tumor (1 paper, 2024). A well differentiated, low, intermediate, or high grade neoplasm with neuroendocrine differentiation that arises from the colon or rectum. "For example, CLDN3 positivity was described in 95% of 20 and in 89% of 57 esophageal adenocarcinomas (our study: 93.4%), 100% of 16 colorectal neuroendocrine tumors (our study: 100%), and in 97% of 34 pulmonary adenocarcinomas (our study: 96.2%)." (PMID 39658782, 2024).
congenital heart disease (1 paper, 2021). A heart disease that is present at birth. "Plasma claudin-3 levels were noted to be increased significantly in pediatric congenital heart disease patients following cardiopulmonary bypass." (PMID 34778138, 2021).
diarrhoea (1 paper, 2022). "It is possible that the increased expression of CLDN3 reduced the translocation of bacteria across the intestinal barrier, while the increased expression of MUC2 reduced the adherence of bacteria to the intestinal cells, thereby reducing the risk of pigs to infection and diarrhoea." (PMID 36258027, 2022).
dyslexia (1 paper, 2025). A learning disorder characterized by an impairment in processing written words. "The CLDN3 variant was nominally significantly associated with dyslexia when comparing the discovery and RD cases with either the TD cohort (P = 0.03) or the general population (i.e. gnomAD data; P = 0.003)." (PMID 41442065, 2025). "The patterns in family 10 and 18 are consistent with a dominant effect of the CLDN3 7–73769649-G-A variant on dyslexia and/or reading difficulties." (PMID 41442065, 2025).
endocervical carcinoma (1 paper, 2023). A carcinoma that arises from epithelial cells of the endocervix. "As the expression of KRT14 and CLDN3 showed high consistency in both scRNA‐seq and 3D organoids, exhibiting clinical value, we further verified their heterogenous expression using TCGA cervical and endocervical cancer (CESC) dataset and clinical samples from our center." (PMID 36725337, 2023).
endometrial adenocarcinoma (1 paper, 2018). "In endometrial adenocarcinoma claudin-3 and -4 mRNA and protein increased with the clinicopathologic features of the tissue, progressing from simple to complex and from atypical hyperplasia to endometrioid carcinoma." (PMID 30061539, 2018). "This is supported by the finding that the cytotoxicity of CPE was even enhanced in an endometrial adenocarcinoma cell line after upregulation of claudin-3 and -4." (PMID 30061539, 2018).
endothelial dysfunction (1 paper, 2024). In vascular diseases, endothelial dysfunction is a systemic pathological state of the endothelium (the inner lining of blood vessels) and can be broadly defined as an imbalance between vasodilating and vasoconstricting substances produced by (or acting on) the endothelium. "Claudin 3 levels correlated with nitrite levels but not with the other endothelial dysfunction biomarkers." (PMID 38396668, 2024). "In our study, the level of claudin 3 was significantly correlated with the level of nitrites, but not with the other biomarkers of endothelial dysfunction." (PMID 38396668, 2024).
esophageal varices (1 paper, 2024). Abnormally dilated veins of the esophagus. "There were no significant changes in the level of the intestinal barrier marker claudin 3, international normalized ratio, and the prevalence of esophageal varices in these patients." (PMID 38337613, 2024). "There was no significant decrease in the level of the intestinal barrier marker claudin 3, international normalized ratio, total bilirubin, alanine aminotransferase in any of the groups, nor were there significant changes in the prevalence of esophageal varices." (PMID 38337613, 2024).
gallbladder diseases (1 paper, 2022). "Proteins in the bile EV of 20 patients with benign and malignant gallbladder diseases were determined by Proteomics analysis, in order to evaluate the expression of CLDN3, showing that CLDN3 is a candidate diagnosis of CCA with an AUC of 94.5%." (PMID 36010914, 2022).
HELIX syndrome (1 paper, 2024). "This replacement of CLDN10b by CLDN3 is reminiscent of the situation in HELIX syndrome patients." (PMID 38731882, 2024). "In the absence of CLDN10b from these segments, e.g., in CLDN10b knockout mice and in TAL from a HELIX syndrome patient, CLDN3 (together with two further claudins, CLDN-16 and -19) is present in all TJ segments, i.e., also in those that are normally occupied by CLDN10b." (PMID 38731882, 2024).
hemorrhagic stroke (1 paper, 2021). A stroke caused by a bleed on the brain. "The expression of nuclear β-catenin and TJ proteins claudin-3 were decreased in endothelial cells of brain lesions in patients with hemorrhagic stroke." (PMID 34565396, 2021).
hypersplenism (1 paper, 2024). Overactive functioning of the spleen, resulting in excessive destruction of blood cells. "In addition, patients with elevated levels of claudin 3 had more severe splenomegaly and hypersplenism; this is possibly related to the spleen’s response to increased molecular bacterial translocation." (PMID 38543514, 2024).
Hypocalciuria (1 paper, 2024). An abnormally decreased calcium concentration in the urine. "In summary, our study does not provide evidence for altered Pi handling and homeostasis in Cldn3 KO mice, though calcitriol is increased and associates with hypocalciuria in Cldn3 KO mice challenged with high dietary Pi." (PMID 39115555, 2024).
idiopathic pulmonary fibrosis (1 paper, 2010). Idiopathic pulmonary fibrosis (IPF) is a nonneoplastic pulmonary disease that is characterized by the formation of scar tissue within the lungs in the absence of any known cause. "In our previous study with samples from normal human adult lung, sarcoidosis and idiopathic pulmonary fibrosis (IPF) claudin-3, -4 and -7, but not claudin-1, were positive in normal type II pneumocytes, a finding which is in agreement with the results of the present study." (PMID 20478039, 2010).
injury (1 paper, 2022). Damage inflicted on the body as the direct or indirect result of an external force, with or without disruption of structural continuity. "Alterations in expression of the tight junction genes claudin-3 and claudin-4 occurs within 3 days of IR in parotid glands, and increased claudin-4 expression accompanies acute lung injury." (PMID 36263624, 2022).
intracerebral hemorrhage (1 paper, 2014). A cerebrovascular disorder characterized by bleeding into one or both cerebral hemispheres including the basal ganglia and the cerebral cortex. "A recent study showed downregulated claudin-3 after 24 h after the surgery in a mouse model of intracerebral hemorrhage." (PMID 25389390, 2014).
leukoaraiosis (1 paper, 2021). "Our results revealed that in addition to SOX10, the expression levels of claudin-1, claudin-3, and myelinogenesis-related proteins were prominently downregulated in leukoaraiosis patients, compared to those in healthy controls." (PMID 34008771, 2021). "Our data has demonstrated that the abnormal expression of claudin-1 and claudin-3 regulates the pathological progression of leukoaraiosis by governing the viability and myelination of oligodendrocytes." (PMID 34008771, 2021). "However, the roles of claudin-1 and claudin-3 in oligodendrocytes and leukoaraiosis are still not well-defined." (PMID 34008771, 2021).
liver fibrosis (1 paper, 2023). "Unexpectedly, GSEA showed that cell junction assembly of hepatic LyECs was upregulated after liver fibrosis, and tight junction protein Claudin-3 (Cldn3) expression was upregulated." (PMID 36632228, 2023). "However, GSEA showed that cell junction assembly of hepatic LyECs was upregulated after liver fibrosis, and tight junction protein Claudin-3 (Cldn3) expression was upregulated." (PMID 36632228, 2023).
Menière’s disease (1 paper, 2017). "Our results indicate a high relevance of Claudin 3 and Claudin 4 as important paracellular barrier molecules in the ED and ES epithelium with potential involvement in the pathophysiology of Menière’s disease." (PMID 28374851, 2017).
metabolic syndrome (1 paper, 2025). A cluster of metabolic risk factors for CARDIOVASCULAR DISEASES and TYPE 2 DIABETES MELLITUS. "Men tend to accumulate visceral adiposity (VAT), which is associated with increased metabolic syndrome and cardiovascular risk, expressed as elevated serum lipopolysaccharide (LPS) levels and decreased expression of tight junction proteins (ZO-1, Occludin and Claudin-3), and widening of cell gaps." (PMID 40800131, 2025).
mucinous cystadenocarcinoma (1 paper, 2017). An invasive adenocarcinoma characterized by cystic changes and the presence of malignant glandular cells which contain intracytoplasmic mucin. "For instance, a recent study showed that EGF induced downregulation of CLDN3 in mucinous cystadenocarcinoma via the MEK/ERK or PI3K/Akt signaling pathway by inducing degradation of the TJ proteins with changes in structures and functions." (PMID 28160565, 2017).